FASN (fatty acid synthase)
Diseases named in the same sentence as FASN in open-access papers (continued):
Sharing a sentence is not in itself a finding about the gene and the disease.
ovarian carcinoma (continued). "Therefore, FASN is proposed as a metabolic marker for ovarian cancer proliferation." (PMID 33194756, 2020). "Therefore, inhibition of TAK1/NF-κB signaling by 5Z-O or suppression of AMPK/ACC/FASN signaling in lipogenesis by the potent AMPK activator PF-0640957752 or orlistat could inhibit ovarian cancer dissemination and tumor growth in vivo." (PMID 31372520, 2019). "Orlistat decreased tumour fatty acid metabolism by inhibiting FASN, cisplatin reduced fatty acid β‐oxidation, and combination treatment delayed tumour growth and induced apoptotic and necrotic cell death in cisplatin‐resistant ovarian cancer cells over and above that with either treatment alone." (PMID 29569717, 2018). "In addition, there are studies on ovarian cancer cell lines showing that FASN activity modulates Akt activation, and, at the same time, Akt activation regulates FASN expression, suggesting that the Akt activation protects cells against FASN inhibitor induced cell death." (PMID 24778702, 2014). "Thus, the C93-induced apoptosis in ovarian cancer cells may be related to FASN inactivation and/or suppression of AKT activity." (PMID 20508725, 2010). "Thus, ovarian cancer cells that overexpress FASN are molecularly dependent on it for cell survival." (PMID 20508725, 2010). "How FASN contributes to disease aggressiveness in ovarian cancer remains speculative." (PMID 20508725, 2010). "Further, ubiquitination assays showed that USP43 reduced FASN ubiquitination in ovarian cancer cell lines and The C110S mutant attenuated the ability of USP43 to hydrolyze ubiquitin chains on FASN." (PMID 40890129, 2025). "The enantiomer (–)-UB006 displays a potent cytotoxic effect in several tumor cell lines, particularly the ovarian cancer OVCAR-3 cell line, with a 40-fold increase in potency compared with the fatty acid synthase (FAS) inhibitor C75." (PMID 40006009, 2025). "FASN and SCD1 are two critical enzymes in fatty acid production that are overexpressed in ovarian cancer." (PMID 40868085, 2025). "As expected, cardamonin decreased the level of free fatty acids and the protein expression of SREBP1, FASN, ACC, and ACLY, indicating that cardamonin inhibited DNL in ovarian cancer cells." (PMID 40315213, 2025). "Recently, novel FASN inhibitors (TVB-3166 and TVB-2640) have shown significant anticancer potential and lower systemic toxicity in BC, ovarian cancer, non-small cell lung cancer, and colorectal cancer." (PMID 41421797, 2025). "Pharmacological inhibition of FASN using orlistat, C75, and TVB-2640 had achieved significant effects in ovarian cancer treatment as well as reversing chemotherapy resistance." (PMID 40709184, 2025). "FASN also contributes to epithelial-mesenchymal transition (EMT) by regulating the expression of E-cadherin and N-cadherin in ovarian cancer." (PMID 41203126, 2025). "Our results demonstrate that the expressions of FASN and SCD1 are also elevated in ovarian cancer tissues." (PMID 37712874, 2023). "The results showed that the gene expression of several enzymes related to fatty acid metabolism, such as SCD1, FASN, and ELOVL, were altered in ovarian cancer tissues." (PMID 37712874, 2023). "Suppressing the expression of FASN using FASN inhibitors downregulated HER2 mRNA and reduced the tyrosine kinase activity in ovarian cancers with HER-2 overexpression." (PMID 37110218, 2023). "SCD1 and FASN expressions were higher and ELOVL1–6 and FADS1 expressions were lower in ovarian cancer tissue, while ACC1 and FADS2 were unchanged." (PMID 37712874, 2023). "The co-expression of FASN and HER-2 tends to reduce the 5-year survival rate in patients who are diagnosed with ovarian cancer." (PMID 37110218, 2023). "For instance, an increase in fatty acid synthase (FASN) can increase resistance to cisplatin in breast and ovarian cancer." (PMID 37612627, 2023).
ovarian carcinoma (continued). "Consistent with the TCGA database expression trend, FASN expression was significantly higher in COAD, UCEC, and PAAD, and demonstrated a decreasing trend in comparison with normal samples in BRCA, ovarian cancer, GBM, liver cancer, and lung cancer." (PMID 36555243, 2022). "Restoration of miR-33b negatively regulated the TAK1/fatty acid synthase (FASN)/carnitine palmitoyltransferase 1A (CPT1A)/NF-κB signaling axis, leading to suppression of peritoneal metastases of ovarian cancer." (PMID 34638280, 2021). "Mechanistically, miR-33b directly targets TAK1, thereby decreasing the expression of FASN and CPT1A in ovarian cancer cells, which reduces OCM-promoted fatty acid synthesis and ATP production." (PMID 34638280, 2021). "Mechanistic studies emphasized that miR-33b directly targets TAK1, which leads to downregulation of FASN and CPT1A, explaining the inhibitory effects of miR-33b on the lipid metabolic activities of ovarian cancer cells." (PMID 34638280, 2021). "Fatty acid synthase (FASN) is a key metabolic enzyme regulating de novo fatty acid synthesis, which is crucial for the OCM-induced oncogenic properties of ovarian cancer in vitro and in vivo." (PMID 34638280, 2021). "Our present study observed that depletion of TAK1 leads to decreased FASN and CPT1A expression, and consequently, this inhibition of lipid metabolic activities results in suppression of NF-κB activation in OCM cocultured ovarian cancer cells." (PMID 34638280, 2021). "Interestingly, DDR2 knockdown significantly abrogated COL11A1-induced FASN overexpression while ITGA1 knockdown only slightly reduced FASN expression (data not shown), suggesting that DDR2 might be the predominant receptor that mediates COL11A1-induced FASN expression in ovarian cancer cells." (PMID 32312965, 2020). "Consistently, the depletion of FASN caused a remarkable reduction of cell proliferation, cell migration, and invasion of ovarian cancer cells in OCM, indicating FASN is another key target for the oncogenic properties of ovarian cancer cells in OCM." (PMID 31372520, 2019). "The present study was designed to explore the cross talk between fatty acid synthase (FASN) and HER2 (ErbB2) in ovarian cancer." (PMID 25433947, 2015). "Therefore, the present results regarding FASN overexpression and FASN inhibitor cytotoxic effects in chemosensitive, but also in platinum-resistant ovarian cancer cells make an important contribution and may have an impact on treatment in the foreseeable future." (PMID 25947066, 2015). "Nevertheless, to confirm the finding that FASN and HER2 expressions were correlated in ovarian cancer, patients were divided into high expression of FASH (high)/HER2 (high) and FASN (high)/HER2 (Low) group." (PMID 25433947, 2015). "However, the mechanisms by which FASN favors the progression of ovarian carcinoma remain unknown." (PMID 24979135, 2014). "Previous work has shown that pharmacological inhibition of FASN with C93, a C75 derivative, activates AMP-activated protein kinase (AMPK) in SKOV3 human ovarian cancer cells." (PMID 25313139, 2014). "MT19c treatment downregulated FASN and ACC activation both in in-vitro and in-vivo models of ovarian cancer." (PMID 22509304, 2012). "In order to assess the biological significance of NAC1-dependent FASN expression, we stained tumor samples obtained from ovarian cancer ascites and tissues for NAC1 and FASN and correlated their immunointensities." (PMID 20508725, 2010). "Therefore, de novo FAs synthesis is upregulated in ovarian cancer, driven by increased ACLY, ACC, and FASN-mediated enzymatic activity, which promotes proliferation, metastasis, and chemoresistance." (PMID 40709184, 2025). "Additionally, other studies reported a dual-directional connection between FASN and AKT/mTORC1 in colorectal, HCC, and ovarian carcinoma in vitro." (PMID 36765520, 2023).
ovarian carcinoma (continued). "Furthermore, elevated fatty acid synthase (FASN), a crucial enzyme in de novo lipid synthesis, confers more aggressive phenotypes to ovarian cancer." (PMID 37205182, 2023). "Increased AMPK levels were found to inhibit ACC expression and activity, resulting in a decrease in fatty acid synthesis with no change in FASN protein expression, eventually causing cytotoxicity in SKOV3 human ovarian cancer cells after C93 treatment." (PMID 35243817, 2022). "Importantly, FASN or CPT1A suppression results in a reduction in NF-κB activities and, as a consequence, affects the proliferation, migration, and invasion of ovarian cancer cells." (PMID 34638280, 2021). "The FASN inhibitor TVB-3166 can destroy the lipid structure on membrane of cancer cell, inhibit lipid biosynthesis, and promote cancer cell apoptosis through the PI3K-AKT-mTOR and β-catenin signaling pathways in ovarian cancer." (PMID 33194756, 2020). "We observed a dramatic decrease in CPT1A expression and FAO rate in FASN-knockdown ES2 cells, suggesting that fatty acid synthesis might be an upstream regulator of FAO in ovarian cancer cells." (PMID 32312965, 2020). "We next investigated whether targeting AMPK/ACC/FASN-mediated lipogenesis and the AMPK/TAK1/NF-κB signaling cascade suppresses ovarian cancer cell metastasis in vivo using an intraperitoneal xenograft SCID mouse model." (PMID 31372520, 2019). "Similarly, fatty acid synthase (FASN) is also involved in invasion by promoting EMT in breast and ovarian cancer cells, and by interacting with wingless-related integration site (Wnt) signaling in metastatic colorectal cancer cells." (PMID 31277295, 2019). "Taken together, both the ex vivo omental system and in vivo tumor xenograft mouse model support our notion that targeting AMPK/ACC/FASN for lipogenesis and AMPK/TAK1/NF-κB oncogenic signaling is able to inhibit metastatic dissemination of ovarian cancer cells in the peritoneal cavity." (PMID 31372520, 2019). "It was also disclosed that FASN expression level is not correlated with HER2 status in ovarian cancer." (PMID 25433947, 2015). "Inhibition of FASN results in PI3K and downstream mediators to be targeted for degradation by ubiquitilation, leading to cytoreduction and growth arrest in A2780, SKOV3, OVCAR-3 ovarian cancer cell lines." (PMID 23591839, 2013). "Moreover, a positive feedback regulation has been reported in ovarian carcinoma cells between AKT activation and FASN expression." (PMID 20508725, 2010). "Western blot analysis shows a single protein band at the molecular mass of FASN protein in all three ovarian cancer cell lines (OVCAR3, A2780, and SKOV3) but not in a low-grade serous carcinoma cell line, MPSC1, nor in ovarian surface epithelial cells (OSE10)." (PMID 20508725, 2010). "Thus, at least in ovarian cancer cells, the NAC1 pathway represents another mechanism for controlling FASN expression." (PMID 20508725, 2010). "For example, the expression levels of FASN in proliferative non-malignant ovarian epithelial cells and tubal secretory epithelial cells are comparable to that of ovarian cancer cell lines, and inhibitors such as C75 and G28UCM exhibit similar sensitivity against the three cell lines." (PMID 41421797, 2025). "CPT1A, SCD and FASN may form an adjustable lipid metabolism enhancing pathway with CPT1A as the center, which plays a key synergistic role in the development of paclitaxel resistance in ovarian cancer." (PMID 38003694, 2023). "Here, we identified that OCM remarkably enhanced FASN and CPT1A expression in ES-2 cells compared with coculture in 1% FBS-negative control medium, whereas the OCM-mediated upregulation of FASN and CPT1A was attenuated upon overexpression of miR-33b in ovarian cancer cells." (PMID 34638280, 2021). "Interestingly, proteins such as CCNE1, FASN, HDGF, MCM7, PIGR, PTK2, or TRA2B have been described as having a prognostic relation with some other type of gynecological cancer (breast, cervical or ovarian cancer)." (PMID 34680205, 2021).
ovarian carcinoma (continued). "Thus, our data suggest that a lipid-rich microenvironment may cause epigenetic silencing of miR-33b, which negatively modulates ovarian cancer peritoneal metastases, at least in part, by suppressing TAK1/FASN/CPT1A/NF-κB signaling." (PMID 34638280, 2021). "To investigate directly whether FASN signaling within tumor cells could adversely affect anti-tumor T-cell responses, we use an immunocompetent syngeneic mouse model transplanted mouse ovarian cancer cell ID8 with or without knockdown FASN." (PMID 30619288, 2018).
hepatocellular carcinoma (103 papers, 2011 to 2026). A malignant tumor that arises from hepatocytes. "For example, in hepatocellular carcinoma (HCC), FASN expression is often upregulated and associated with poor prognosis." (PMID 40391753, 2025). "IKKβ phosphorylates and stabilizes USP30, promoting USP30-mediated deubiquitination of ACLY and FASN induction, leading to the occurrence of hepatocellular carcinoma." (PMID 39944823, 2025). "In hepatocellular carcinoma, the FASN inhibitor TVB‐3664 demonstrated effective antitumor activity in combination with tyrosine kinase inhibitors commonly used in advanced hepatocellular carcinoma, such as sorafenib." (PMID 40552664, 2025). "FASN inhibitors blocked the FASN-HIF1α-SLC7A11 pathway signaling in hepatocellular carcinoma cells, and delayed tumor growth by inducing apoptosis and necrosis." (PMID 39757995, 2025). "In hepatocellular carcinoma (HCC), Riplet deficiency stabilizes fatty acid synthase (FASN), increasing secretion of palmitic acid (PA/C16:0)." (PMID 40977744, 2025). "MiR-4310 suppressed malignant progression of hepatoma by inhibiting FASN and SCD1-mediated lipid synthesis directly." (PMID 38341418, 2024). "Here, high glucose (HG) conditions were used to study lipid accumulation and fatty acid synthase (FASN) expression in human HepG2 hepatoma cells using Oil Red O and Western blot assays." (PMID 36982278, 2023). "FASN is a rate-limiting enzyme complex that catalyzes de novo lipogenesis, and its level is frequently increased in human hepatocellular carcinoma, which is accompanied by diminished FASN acetylation and is conducive to tumor cell growth." (PMID 36998063, 2023). "KAT8 was shown to acetylate fatty acid synthase (FASN) to further destabilize FASN and decrease de novo lipogenesis and tumor cell growth of human hepatocellular carcinoma." (PMID 36849520, 2023). "ACAT1-mediated acetylation of dihydroxyacetone phosphate acyltransferase (GNPAT) plays a key role in FASN stabilization to increase lipid synthesis in hepatocellular carcinoma." (PMID 36038892, 2022). "The ability of FASN inhibition to reduce the emergence of hepatocellular carcinoma in mice with significant liver injury provides the potential for further evaluation of this treatment for this devastating disease." (PMID 36123383, 2022). "AMPK activation has been found to suppress FASN activity in hepatoma cells, as well as inhibit ACC activity by enhancing phosphorylated ACC levels." (PMID 35243817, 2022). "USP2-1 potentiates the stability of FASN by inhibiting proteasome-dependent degradation in prostate cancer, hepatoma, mantle cell lymphoma, and glioma." (PMID 33530560, 2021). "As hepatocellular carcinoma progression is highly dependent on FASN and its mediated lipogenesis, a relationship was found between FASN expression and OS, PFS, RFS, and DSS in liver cancer patients." (PMID 34879004, 2021). "In hepatocellular carcinoma, fatty acid synthase (FASN) was overexpressed in high metastatic hepatocellular carcinoma cells, and inhibition of FASN contributed to hepatocellular carcinoma metastasis suppression." (PMID 35047398, 2021). "Hepatoma cells also showed lower protein levels of fatty acid synthase and a largely distinct protein electrophoresis profile from hepatocytes but similar between different hepatoma lines." (PMID 32694512, 2020). "Gong et al21 have found that inhibition of FASN in hepatocellular carcinoma cell lines reduces the migration and invasion by reducing the HIF‐1α/IGFBP1 pathway." (PMID 33164330, 2020). "We found that phosphorylation of AMPKα (Thr172) was decreased and that SREBP-1c, ACC1 and FASN mRNA and/or protein levels were increased significantly in mouse hepatic tissues and hepatoma cell lines expressing NS5A." (PMID 31684957, 2019). "In hepatocellular carcinoma triggered by co-expression of Akt and c-Met, their growth was dependent on mTORC1 and fatty acid synthase (FASN)." (PMID 31817676, 2019).